STUM (stum, mechanosensory transduction mediator homolog)
Synonyms: C1orf95; DKFZp761P211
Tractability: Antibody: UniProt predicts a signal peptide or a membrane-spanning region.
Gene: Protein-coding gene on chromosome 1 (226,548,764 to 226,609,230, forward strand). Ensembl gene ENSG00000203685.
Subcellular location: Membrane
Subcellular location (Human Protein Atlas): Cytosol
Gene Ontology:
Molecular function: protein binding
Cellular component: membrane
Genetic constraint (gnomAD): Loss-of-function variants: 8 observed, 13.61 expected, observed/expected ratio (o/e) 0.59, 90% interval 0.34 to 1.06. The upper end of that interval is the gene's LOEUF score, 1.06, which puts it in group 4 of 6, group 1 being the genes least tolerant of losing a copy. Missense variants: 142 observed, 176.98 expected, observed/expected ratio (o/e) 0.8, 90% interval 0.7 to 0.92. Synonymous variants: 78 observed, 71.63 expected, observed/expected ratio (o/e) 1.09, 90% interval 0.91 to 1.32.
Homologues: Orthologues: chimpanzee STUM (100% identical), mouse Stum (98% identical), dog STUM (96% identical), macaque STUM (92% identical), pig STUM (91% identical), tropical clawed frog stum (82% identical), zebrafish stum (77% identical), guinea pig STUM (51% identical), Drosophila melanogaster stum (35% identical), Caenorhabditis elegans Y51H7BR.7 (30% identical).
Diseases named in the same sentence as STUM in open-access papers:
STUM is named in the same sentence as 3 diseases in open-access papers, as found by Europe PMC text mining. Sharing a sentence is not in itself a finding about the gene and the disease. The quoted sentences say what the papers report.
cancer (1 paper, 2024). A tumor composed of atypical neoplastic, often pleomorphic cells that invade other tissues. "In addition, we also identified 6 upregulated genes not typically associated with cancer (ARC, C1orf167, CNGA3, KRT75, SPRR1B, STUM)." (PMID 38038766, 2024).
STUM also shares sentences with these, for which no sentence is quoted: ovarian tumors (1 paper); skin cutaneous melanoma (1).